CACNA1S (calcium voltage-gated channel subunit alpha1 S)
Description:
Pore-forming, alpha-1S subunit of the voltage-gated calcium channel that gives rise to L-type calcium currents in skeletal muscle. Calcium channels containing the alpha-1S subunit play an important role in excitation-contraction coupling in skeletal muscle via their interaction with RYR1, which triggers Ca(2+) release from the sarcoplasmic reticulum and ultimately results in muscle contraction. Long-lasting (L-type) calcium channels belong to the 'high-voltage activated' (HVA) group.
Synonyms: CACNL1A3; Cav1.1; hypoPP; CCHL1A3; CMYO18; CMYP18; DHPRM; HOKPP; HOKPP1; MHS5; TTPP1
Tractability: Small molecule: an approved drug acts on it; a high-quality ligand is known; it belongs to a druggable protein family. Antibody: UniProt places it where antibodies can reach, with high confidence; its Gene Ontology location is reachable by antibodies, with high confidence; UniProt predicts a signal peptide or a membrane-spanning region. PROTAC: a small molecule that binds it is known.
Target class: Voltage-gated calcium channel; Ion channel; Voltage-gated ion channel
Safety:
Unwanted effects reported when the protein is acted on. In parentheses: how it was acted on, where the effect was seen, and who reports it.
Malignant Hyperthermia (source: ClinPGx)
Gene: Protein-coding gene on chromosome 1 (201,039,512 to 201,112,451, reverse strand). Ensembl gene ENSG00000081248.
Subcellular location: Cell membrane, sarcolemma, T-tubule
Subcellular location (Human Protein Atlas): Acrosome; Equatorial segment
Pathways (Reactome):
Developmental Biology: NCAM1 interactions
Gene Ontology:
Molecular function: high voltage-gated calcium channel activity; molecular function activator activity; protein binding; small molecule binding; voltage-gated calcium channel activity; monoatomic ion channel activity
Biological process: calcium ion transport; muscle contraction; release of sequestered calcium ion into cytosol; calcium ion import across plasma membrane; calcium ion transmembrane transport; cellular response to caffeine; positive regulation of muscle contraction; monoatomic ion transport; transmembrane transport
Cellular component: cytoplasm; I band; plasma membrane; T-tubule; voltage-gated calcium channel complex; L-type voltage-gated calcium channel complex; membrane
Genetic constraint (gnomAD): Loss-of-function variants: 117 observed, 209.68 expected, observed/expected ratio (o/e) 0.56, 90% interval 0.48 to 0.65. The upper end of that interval is the gene's LOEUF score, 0.65, which puts it in group 2 of 6, group 1 being the genes least tolerant of losing a copy. Missense variants: 2,329 observed, 2,512.7 expected, observed/expected ratio (o/e) 0.93, 90% interval 0.89 to 0.96. Synonymous variants: 957 observed, 973.22 expected, observed/expected ratio (o/e) 0.98, 90% interval 0.93 to 1.04.
Gene-disease validity (ClinGen):
ClinGen rates the evidence that CACNA1S causes each of these diseases.
malignant hyperthermia, susceptibility to, 5 (autosomal dominant): Moderate.
Homologues: Orthologues: chimpanzee CACNA1S (99% identical), macaque CACNA1S (99% identical), guinea pig CACNA1S (93% identical), mouse Cacna1s (91% identical), rat Cacna1s (90% identical), rabbit CACNA1S (90% identical), dog CACNA1S (89% identical), pig CACNA1S (81% identical), tropical clawed frog cacna1s (71% identical), zebrafish cacna1sa (67% identical), zebrafish cacna1sb (67% identical). Paralogues in human: CACNA1C (65% identical), CACNA1D (65% identical), CACNA1F (59% identical), CACNA1A (41% identical), CACNA1B (41% identical), CACNA1E (41% identical), CACNA1I (26% identical), SCN2A (26% identical), CACNA1H (26% identical), CACNA1G (26% identical), SCN9A (25% identical), SCN1A (25% identical), and 14 more.